BPTF (bromodomain PHD finger transcription factor)
Diseases named in the same sentence as BPTF in open-access papers (continued):
Sharing a sentence is not in itself a finding about the gene and the disease.
tumor (continued). "We observed improved growth of 67NR and 66cl4 BPTF KD tumors with NK cell depletion (anti-asialo-GM1 mAb), but not with CD8+ or CD4+ T-cell depletion, indicating that NK cells are required for reduced BPTF KD tumor growth." (PMID 28969075, 2017). "Pretreatment of tumor cells with bacterial heparinase suppressed the enhanced binding of NCR1-Ig to BPTF KD cells and reduced the enhanced cytolytic activity of NK cells to 66cl4 BPTF KD targets." (PMID 28969075, 2017). "In addition, considering previous reports showing that KD of BPTF attenuates HPSE expression, an enzyme critical for the cleavage of NCR ligands on the surface of tumor cells, we aimed to investigate whether this regulatory effect exists in HCC." (PMID 39935175, 2025). "Upregulated hsa_circRNA_102051 is capable to suppress miR-203a and mediately trigger BPTF expression, which enhances the proliferation, migration, invasion and stemness of CRC cells, activating Notch signaling pathway and eventually promoting tumor growth and metastasis." (PMID 37794386, 2023). "In addition, the average tumor weight was significantly lower in MGC803/BPTF‐KO and HGC27/BPTF‐NC cells (0.175 ± 0.052 g vs 0.738 ±0.194 g, respectively, p < 0.001) than in MGC803/BPTF‐NC and HGC27/BPTF‐OE cells (0.440 ± 0.222 g vs 0.081 ± 0.051 g, respectively; p < 0.001)." (PMID 37863665, 2023). "However, so far, BPTF has not been reported to promote tumor proliferation and lymphatic metastasis by participating in tumor angiogenesis." (PMID 36529788, 2022). "Additionally, expression of circ-BPTF correlated with tumor stage and recurrence, but not with other features, including metastasis and tumor size." (PMID 30103209, 2018). "However, no significant changes in tumor weight were observed after erlotinib and/or AU‐1 treatment in #Rui‐4 models (low BPTF expression) (vehicle versus AU‐1; erlotinib versus erlotinib + AU‐1; vehicle versus erlotinib + AU‐1) (two‐tailed t‐test, NS, no significance; ***, p < 0.001)." (PMID 37863665, 2023). "To evaluate the role of BPTF during tumour progression in vivo, we subcutaneously implanted in C57/BL6 mice BPTF-silenced KPC cells or non-targeted control cells by CRISPRi and evaluated tumour growth." (PMID 35326669, 2022).
neurodevelopmental disorder (4 papers, 2020 to 2025). A behavioral and cognitive disorder with onset during the developmental period that involves impaired or aberrant development of intellectual, motor, or social functions. "BPTF is associated with a neurodevelopmental disorder characterized by ID, dysmorphic facies and distal limb anomalies." (PMID 34976023, 2021). "Haploinsufficiency of BPTF in humans leads to the clinical entity known as neurodevelopmental disorder with dysmorphic facies and distal limb anomalies (NEDDFL, MIM#617755)." (PMID 33522091, 2021).
neurodegenerative disease (3 papers, 2016 to 2022). A disorder of the central nervous system characterized by gradual and progressive loss of neural tissue and neurologic function. "In patients with neurodegenerative diseases, high expression levels of BPTF have been detected." (PMID 36505780, 2022). "High levels of BPTF were detected in fetal brain and in patients with neurodegenerative diseases." (PMID 29467591, 2018).
infection (1 paper, 2015). The state of being infected such as from the introduction of a foreign agent such as serum, vaccine, antigenic substance or organism. "Similar results were observed following infection with lentiviral vectors expressing two different shRNAs directed against BPTF both of which led to diminished BPTF levels whereas MITF expression was unaffected." (PMID 26440048, 2015).
BPTF also shares sentences with these, for which no sentence is quoted: microcephaly (4 papers); and speech delay (2); Burkitt lymphoma (2); neuroblastoma (2); acute lymphoblastic leukemia (1); angiosarcoma (1); B-cell lymphoma (1); brain abnormalities (1); brain malformations (1); brain tumor (1); cervical cancer (1); congenital myopathies (1); diabetic nephropathy (1); dyslipidemia (1); Expressive language delay (1); fatty liver (1); ganglioneuroblastoma (1); infectious disease (1); intrauterine growth restriction (1); lung disease (1); muscular dystrophies (1); neuro-degenerative diseases (1); neuroblastic tumor (1); Obesity (1); prostate tumor (1); rectal cancer (1); T-cell acute lymphoblastic leukemia (1); X-linked disease (1).